ROCK1 (Rho associated coiled-coil containing protein kinase 1)
Diseases named in the same sentence as ROCK1 in open-access papers (continued):
Sharing a sentence is not in itself a finding about the gene and the disease.
tumor (continued). "Besides, ROCK1 has been found to promote migration, metastasis, and invasion of tumor cells and also to facilitate morphological cell shape transformations through modifications of the actinomyosin cytoskeleton." (PMID 31438847, 2019). "Furthermore, it has been reported that lncRNA UCA1 suppresses the tumor suppressor miR-145 for tumor cell invasion/migration through the expression of miR-145 target proteins such as ROCK1 in glioma cancer cells." (PMID 31293964, 2019). "Furthermore, we found that rho-associated, coiled-coil-containing protein kinase 1 (ROCK1) is one of the functionally relevant targets of LOC441178 in squamous cells, which is negatively correlated with LOC441178 in tumor tissues from OSCC patients." (PMID 30364063, 2018). "In addition, studies indicated hypoxia promoted tumor cell motility via RhoA and ROCK1 signaling pathways." (PMID 28184030, 2017). "Further study into more potent ROCK1 inhibitors may give insight into the cell type-specific activity by which ROCK1 mediates tumor progression in vivo." (PMID 28841710, 2017). "ROCK1 siRNA also significantly inhibited PANC-1 tumor cell migration." (PMID 28841710, 2017). "To evaluate the effects of ROCK1 inhibition in a model more relevant to the in vivo environment, in which both tumor cells and CAFs are grown together, we treated co-cultured SU.86.86 cells with CW-1 cells, and tested the effects of fasudil on phenotypic properties of the cultured cells." (PMID 28841710, 2017). "Moreover, recent studies show that ROCK1/2 also have other roles in cell division and in promoting tumour growth." (PMID 26950944, 2016). "Furthermore, ROCK1 was validated as a direct functional target miR-340 and silencing of ROCK1 phenocopied the anti-tumor effect of mR-340." (PMID 25831237, 2015). "Furthermore, miR-144 appears to function as a tumor suppressor in the development and progression of OS via downregulation of ROCK1 and ROCK2." (PMID 25912304, 2015). "It has been reported that IL-6 promotes tumor cell migration and invasion, and that ROCK1 may be involved in this process." (PMID 25723491, 2015). "ROCK1 immunostaining was heterogeneous and cytoplasmic in all tumour extensions and positive in the invasive front of all cases (100%) and in 92 central tumours (95.8%)." (PMID 25380619, 2014). "In addition, patients with up-regulation of miRNA-135a expression had significantly lower levels of ROCK1 protein expression than those with down-regulation of miRNA-135a (mean tumor to normal ratio, 0.81 vs. 1.55, p<0.001)." (PMID 24465504, 2014). "Patients with lower expression of ROCK1 in the central tumour and invasive front had lower recurrence-free survival rates (p = 0.004 and p = 0.001, respectively), and those with weak ROCK1 expression in the invasive front experienced lower cancer-specific survival (p <0.001)." (PMID 25380619, 2014). "Also, ROCK1 HScores were higher in normal epithelium versus the tumour areas in a subset of samples (n = 21) (p < 0.001)." (PMID 25380619, 2014). "ROCK1 is lower expressed in tumour tissue when compared with adjacent normal vulvar epithelia." (PMID 25380619, 2014). "Furthermore, use of DAPT increased the expression of ROCK1 and 2, supporting the idea that Notch1 normally controls these genes in keratinocytes to prevent tumour progression." (PMID 22583596, 2012). "In conclusion, this is the first report to show that miR-584 functions as a tumour suppressor, directly targets oncogene ROCK-1 and decreases cell motility in RCC cells; we have also shown that miR-584 and ROCK-1 expressions are inversely correlated in primary ccRCC tissues." (PMID 21119662, 2011). "To validate whether miR-584 has a tumour suppressive role through ROCK-1 knockdown, we knocked down ROCK-1 in A-498 and 769-P cells using a si-RNA technique and did functional analysis with these cells." (PMID 21119662, 2011). "Furthermore, LINC01087 knockdown reduced GTP‐RhoA and ROCK1 levels in tumor tissues." (PMID 39023191, 2024).
tumor (continued). "Previous studies have demonstrated that emodin could inhibit RhoA and Rock1 on gene and protein levels, and it can also suppress the phosphatidylinositol 3-kinase-Cdc42/Rac1 pathway, resulting in the restrained migratory movement of tumor cells." (PMID 36969843, 2023). "Besides, abnormal activation of ROCK1 can enhance tumor cell migration." (PMID 35586060, 2022). "Therefore, we believe that RhoA is a downstream regulator of LEMD1, and LEMD1 could affect cytoskeleton changes and tumor cell migration in part through the RhoA/ROCK1 signaling pathway." (PMID 35619906, 2022). "Notably, it is also reported that ROCK1 can phosphorylate ERK2 to promote tumor metastasis." (PMID 35626071, 2022). "All together, these findings demonstrate that ROCK1 downstream of DR5 agonists plays an important role to help mobilize (potentially via CMTM6 or other unknown mechanisms) the internally stabilized PD‐L1 on tumor cell surface." (PMID 33587338, 2021). "Moreover, enrichment in Myosin II activity and ki-67 positive cells was found in IFs of A375M2 tumours, suggesting that the amoeboid phenotype sustained by ROCK1/2-Myosin II could, in principle, support tumour formation and tumour dissemination." (PMID 33082334, 2020). "Interestingly, inhibitors of ROCK1 improve the success rate of bringing embryonic stem cells into culture and are supplemented to the medium for in vitro cultures of human colon epithelial organoids, indicating that inhibition of ROCK1 supports early stages of tumor development." (PMID 26375816, 2015). "Finally, it would also be of interest to determine if combining ROCK1 deficiency with antioxidants only provides synergistic protective effects to normal cells, without reducing the tumor cell-killing ability of anti-tumor drugs including doxorubicin." (PMID 24595357, 2014). "Pharmacological ROCK1 inhibition (for example, with fasudil or Y‐27632) reduced N‐SREBP1 abundance, dampened lipid synthesis, and curtailed tumor growth in vitro and in vivo." (PMID 41144804, 2026). "MiR-335-5p has tumor suppressive functions in several types of cancer, including HCC (see36 for a review), inhibiting expression of proteins like ROCK1 or MAPK1, implied in the regulation of cellular migration and/or proliferation." (PMID 41487453, 2026). "This detrimental effect is attributed to the suppression of CD8+ TIL activity and activation of the ROCK1/2‐PI3K/Akt signaling pathway, which facilitates tumor metastasis." (PMID 41085102, 2025). "Through HIF‐1α/RhoA/ROCK1 signaling, DDR1 promoted cytoskeleton reorganization to induce tumor metastasis." (PMID 39024501, 2024). "Consequently, we hypothesize that ROCK1 serves as a critical molecular mediator in the upregulation of PD‐L1 by IBA, where IBA binds to and activates ROCK1, thereby triggering the downstream c‐Myc/PD‐L1 pathway and ultimately affecting the tumor immune microenvironment." (PMID 39503247, 2024). "Considering the 2 ROCK isoforms, ROCK1-mediated p-MLC activation leads to pericyte differentiation, which stabilizes vessels, whereas ROCK2 signaling in tumor pericytes seems to impair vascular function." (PMID 39286984, 2024). "Out of 21 ICD-related genes with notably different expressions, seven genes, namely ROCK1, BCL2, TLR2, TLR9, AGER, CASR, and P2RX7, were found to have decreased expression in tumor samples, while the rest were upregulated." (PMID 37932362, 2023). "Noncanonical pathways involves Wnt/β-catenin, PI3K/Akt, RhoA/ROCK1, MAPK/p38 or MAPK/ERK1/2 that mediate different effect of TGF-β on different tumor cells." (PMID 36614238, 2023).
tumor (continued). "To dissect the dynamic changes of both kinases and phosphoproteins in PDAC, we performed kinase–substrate enrichment analysis (KSEA), and four kinases (HIPK2, ROCK1, PRKCD, MAPKAPK2) were identified as tumor-specific activated." (PMID 36434634, 2022). "Taken together, these observations indicate that the caspase-cleavage of ROCK1 is required to limit innate and adaptive immune responses to acute DEN-induced liver damage and spontaneous apoptosis in HCC tumours." (PMID 36497425, 2022). "Taken together, circ_PIP5K1A increased the sensitivity of tumor to DDP in vivo through modulating the miR-493-5p and ROCK1 expression." (PMID 34537072, 2021). "Further, ROCK1 can activate LIMK, which inhibits cofilin, leading to actin cytoskeletal remodeling and tumor cell invasion." (PMID 34530870, 2021). "The differential expression of ROCK1 in SCLC and non-tumor tissues was analyzed by performing qPCR and paired t test." (PMID 34271873, 2021). "Inhibition of this pathway with the ROCK1 inhibitor Y-27632 suppressed BTIC enrichment and VM formation, leading to significant inhibition of tumor growth." (PMID 34285210, 2021). "Our results demonstrate that zinc phthalocyanine (ZnPc)-PDT with 12 J/cm2 or 24 J/cm2 irradiation can substantially decrease tumor migration via downregulating MMP9 and ROCK1 and inhibit the clonogenicity of SW480 cells via downregulating CD44 and SOX2." (PMID 34833970, 2021). "We discovered early activation of ROCK1 and myosin light chain phosphorylation by all DR5 agonists in various tumor lines (and EV3C–G)." (PMID 33587338, 2021). "Correlations between MCM3AP-AS1 and ROCK1 across SCLC and non-tumor tissues were analyzed, and the results indicated that MCM3AP-AS1 and ROCK1 levels were positively correlated in both SCLC and non-tumor tissues." (PMID 34271873, 2021). "Recently, a number of studies have reported that miR-340 plays a critical role in tumor initiation and progression, by targeting multiple oncogenes such as SKP2, FHL2, c-Met, and ROCK1." (PMID 33390846, 2021). "It has been documented that ROCK1 favored tumor development via enhancing the invasive and motility abilities and promoting EMT of tumor cells." (PMID 34836544, 2021). "In contrast its downregulation in circulating tumor cells (CTCs) suppresses tumor dissemination through modulation of the expression of ITGAV and ROCK1." (PMID 32013263, 2020). "ROCK1 and ROCK2 are the negative regulators of the Hippo tumor suppressor pathway, and while activation of the Rho/Rock signal can increase YAP activity in pleural mesothelioma, ROCK2 knockout decreased tumor volume in a mouse model of osteosarcoma." (PMID 33178014, 2020). "Using online algorithms, we were able to predict potential miR-361 target genes involved in cancer metastasis, such as MEF2D, ROCK1 and WNT7A, and the tumor microenvironment, including KPNA4, PDE4B and VEGF-A." (PMID 31287002, 2019). "Scenario 3 included ROCK1 expression, preoperative PSA, clinical tumor stage (cT stage) and Gleason grade obtained on the prostatectomy specimen." (PMID 31557128, 2019). "The mechanistic studies in vivo indicated that ROCK1/PTEN/PI3K/Akt signaling pathway-regulated GSK3β dephosphorylation and apoptosis are involved in hirsutine-inhibited tumor growth in an A549 xenograft mouse model." (PMID 29789524, 2018). "Many HBV integration events occurred near or within fragile sites and other repetitive regions, such as TERT, FN1, MLL4, ROCK1, CCNE1, SENP5, Alu sequences, and microsatellites, which are prone to tumor development and progression." (PMID 28382278, 2017). "Indeed, ROCK1 may be playing an active role in both tumor and stromal cells." (PMID 28841710, 2017). "In contrast its downregulation in Circulating Tumor Cells (CTC), suppresses tumor dissemination through modulation of the expression of ITGAV and ROCK1." (PMID 28118616, 2017).
tumor (continued). "There are many validated miRNA-148a’s target genes contributing to the tumor metastatic behavior, including MMP7, ROCK1, SMAD2, Met and cholecystokinin B receptor (CCK-BR)." (PMID 28199399, 2017). "Then, we xenografted ROCK1 knockdown and control SMMC-7721 cells in the nude mice, and observed that knockdown of ROCK1 suppressed metastasis of tumor cells in the lungs and liver and consequently enhanced mice survival times." (PMID 28978024, 2017). "We then utilized shRNA technology to knockdown the expression of ROCK1 and 2 in SVR tumor-forming vascular cells, and evaluated tumor size and proliferation rate in a xenograft model." (PMID 28709411, 2017). "Consistently, we observed increased ROCK1 protein in HCC cell lines and primary tumor samples compared to normal liver cell line and tissue samples, but the mRNA levels remained unchanged." (PMID 28978024, 2017). "We have previously shown that pharmacological inhibition of both ROCK1 and 2 with Y-27632 reduces SVR tumor size in a xenograft model." (PMID 28709411, 2017). "However, incomplete or specific inhibition of only one isoform of ROCK alone may not be an effective treatment, and may even lead to adverse results as our results also highlight isoform specific tumor suppressive functions for ROCK1 in lung and ROCK2 in melanoma models." (PMID 26765561, 2016). "Overall, it appears that within the systems studied ROCK1 and ROCK2 perform the same roles, and that ROCK proteins are indispensable for cell proliferation and hence tumor development." (PMID 26765561, 2016). "Other recent studies have also revealed functional differences between ROCK1 and ROCK2 in regulating the actin cytoskeleton and other cellular functions in non-tumor cells." (PMID 26725045, 2016). "Second, we searched for the target oncogenes of the tumor suppressor miR-584-3p in PITA (Segal Lab of Computational Biology) and identified a potential target oncogene, ROCK-1." (PMID 26715733, 2016). "The deleted 18p11.21 region contains important tumor inhibitory genes, for example EPB41L3, L3MBTL4, ARHGAP28, PTPRM, and ROCK1 (for complete list of genes in deletion regions)." (PMID 22363777, 2012). "Moreover, ATOX1/ROCK1-targeted drugs’ therapeutic effects were further investigated in the LLC allogeneic transplantation model and MNU-induced tumour model." (PMID 40940984, 2025). "There are many studies reporting on the mechanisms for lycorine to inhibit tumor cell growth and induce apoptosis, which involve target molecules such as MEK2, ROCK1, and miR-186/CDK1; however, it remains unclear which molecule has the main role." (PMID 38434975, 2024). "IBA upregulated the expression levels of PD‐L1 in the anti‐PD‐L1 antibody treatment group, activated the ROCK1/c‐Myc/PD‐L1 axis, and suppressed the activation of CD8+ cells within the tumor microenvironment, reversing the improvement of TILs in mouse tumor tissues." (PMID 39503247, 2024). "Indeed, miR-584-5p exerts tumor suppressor properties in cervical carcinoma and in clear cell renal carcinoma (ccRCC) tissues, impairing the expression of GLI1 and of ROCK1, respectively." (PMID 39000555, 2024). "In our study, scRNA‐seq data showed that the RhoA/ROCK1 pathway was obviously enriched in OXA‐resistant GC samples, suggesting that RhoA/ROCK1 may play a key role in tumor matrix stiffness." (PMID 39392399, 2024). "However, mutations in RhoA are not frequent and accumulating evidence supports a role for its regulators including ARHGEF2 as well as the effectors ROCK1/2 and MLCK in tumor development and progression." (PMID 38970683, 2024). "Whether low-ROCK1 expression in PMOP influences the immune microenvironment and then alters the tumor’s features should be further investigated." (PMID 37683138, 2023). "But the ROCK1 expression was not related to other clinicopathological characteristics such as age (P = 0.122), tumor size (P = 0.232) or gender (P = 0.521)." (PMID 36197602, 2022).
tumor (continued). "We speculated that the RhoC/ROCK1 pathway activated by TEM8 could activate SMAD5, which was involved in the stemness of tumor cells and tumor angiogenesis." (PMID 34285210, 2021). "In these tissue samples (n = 13), only four genes ID4, HMGCR, ROCK1, and CPT1A were differentially expressed (unadjusted p < 0.01), and no gene expression signatures were significantly different between primary tumor and baseline metastasis samples." (PMID 33428680, 2021). "We further observed an overall negative association between NME4 and tumor invasion markers like genes encoding matrix-degrading proteases (MMP7, ADAM17) and actin cytoskeleton remodelers (ROCK1, ROCK2, LIMK2, CFL2, MYO5A)." (PMID 34674701, 2021). "Furthermore, miR-361 also suppressed the expression of multiple prometastatic genes and tumor microenvironment-related genes, including MEF2D, ROCK1, WNT7A, VEGF-A, PDE4B, and KPNA4." (PMID 31287002, 2019). "Furthermore, we found that MKRN2 inhibited cell migration and invasion in NSCLC cells by regulating the expression of RhoA/ROCK1 and MMP9, thereby influencing the malignant behavior of tumor cells." (PMID 30103781, 2018). "The following in vitro and in vivo assays demonstrated that miR-199a/b-5p was a critical tumor suppressor in HCC that post-transcriptionally inhibited ROCK1 expression and thereby inhibited ROCK1/MLC and PI3K/AKT pathways that are necessary for HCC progression." (PMID 28978024, 2017). "Our data showed that mRNA expression levels of ROCK1 were similar in primary tumor and matched non-tumor liver samples as well as in HCC cell lines." (PMID 28978024, 2017). "By immunohistochemical (IHC) analysis, we observed an increased expression of ROCK1 protein in the majority of PDAC patients, with increased expression in both the tumor epithelial compartment and stromal cells, relative to adjacent normal pancreas, or normal pancreas tissues." (PMID 28841710, 2017). "These putative tumor suppressor functions of Rock1 and Rock2 do not appear to be a consequence of differential expression as the absolute concentration of the two isoforms was found to be similar by SRM." (PMID 26765561, 2016). "ROCK1 and ROCK2, both containing a miR-144-binding site in the 3′-UTRs, were selected for further experimental validation, in view of their critical roles in tumor cell proliferation and invasion." (PMID 25912304, 2015). "Similarly, enrichment of ROCK1 and ROCK2 proteins were detected chiefly in tumor tissues, relative to normal bone tissues." (PMID 25912304, 2015). "MiR-148a was found to bring about tumor-suppressive effect by targeting NRP1, ROCK1 and DNMT1." (PMID 26097868, 2015). "Patients with LN metastasis had a significantly higher expression of ROCK1 protein than those without LN metastasis (mean tumor to normal ratio, 1.86 vs. 0.93, p = 0.007)." (PMID 24465504, 2014). "Tumor weight was significantly reduced in ROCK1 & 2 knockdown tumors compared to control tumors, with ROCK2 shRNA tumors displaying smaller tumors than those formed by ROCK1 knockdown cells." (PMID 22934846, 2013). "Although tumour grade and stage were related to RhoC and ROCK-1 in ccRCC, they were not related to RhoB." (PMID 21119662, 2011). "The neutrophil-mediated damage amplification in Rock1 NC mice following DEN administration had the effect of eliminating potential tumour-initiating cells; by reducing neutrophil recruitment immediately after DEN treatment, there were increased HCC tumour numbers in the long term." (PMID 38616733, 2024). "A recent study has shown that while the loss of either ROCK1 or ROCK2 had no negative impact on tumorigenesis in mouse models of non-small cell lung cancer and melanoma, the loss of both isoforms blocked tumor formation owing to inhibiting cell cycle progression and tumorigenesis." (PMID 35043239, 2022). "Together, this suggests that the effect of RhoA on tumor cell proliferation could be independent of its downstream effectors ROCK1 and ROCK2." (PMID 29535813, 2018).